TNF (tumor necrosis factor)
Diseases named in the same sentence as TNF in open-access papers (continued):
Sharing a sentence is not in itself a finding about the gene and the disease.
asthma (continued). "Also, it was positively correlated with Th1-associated TNF-α, IL-1β and Th17-associated IL-17 to enhance the exacerbation risk of asthma, which showed its potential to regulate Th1 inflammation in asthma." (PMID 33013382, 2020). "An epidemiological study linked phthalate exposure to lower DNA methylation of TNFα which is an inflammatory cytokine that may increase asthma risk in children." (PMID 32435260, 2020). "Genetic variation in tumor necrosis factor (TNF-α) may contribute to childhood asthma and that associations may be modified by parental smoking." (PMID 31921716, 2019). "However, little is known regarding any association between TNF‐α and the occurrence of cell death in asthma." (PMID 30666647, 2019). "Importantly, in vitro and in vivo investigations have also demonstrated that airway inflammation and hyper-responsiveness in asthma are dampened by TNF-α deficiency or antagonism with anti-TNF-α monoclonal antibodies." (PMID 30300399, 2018). "The authors also observed that TNFα hypomethylation was associated with asthmatic children; methylation of the CpG site cg10717214 was negatively associated with asthma in children with AA or AG genotypes for the TNFα rs1800610, suggesting a genetic susceptibility." (PMID 30873799, 2018). "Neutrophils are the key cell type in the immune response to RV infection and have been strongly implicated asthma pathogenesis with neutrophil degranulation associated with asthmatic severity and neutrophilic TNF-α required for the induction of AHR in mouse models." (PMID 25889951, 2015). "On the other hand, that the TLR-agonist-induced increase of AHR in the peripheral parameters was caused by TNFα may be of specific importance since airway closure is linked to excessive bronchoconstriction, recurrent exacerbations and asthma severity." (PMID 26494305, 2015). "Finally, we found that a lower methylation of 5′CGI region of TNFα was associated with asthma in 256 CEAS children (OR = 2.15, 95% CI = 1.01 to 4.62)." (PMID 25960783, 2015). "A lower methylation of TNFα 5′CGI was positively associated with asthma." (PMID 25960783, 2015). "TNF polymorphisms have been associated with asthma and wheeze and were previously reported to modify the association between ozone and asthma in healthy young adults." (PMID 24465030, 2014). "GSTP1 rs1138272 and TNF rs1800629 SNPs were associated with asthma and wheeze, respectively." (PMID 24465030, 2014). "Therefore, we performed a meta-analysis of all eligible studies to obtain more precise estimation of the association of TNF-α rs1800629 polymorphism with asthma susceptibility." (PMID 24936650, 2014). "This meta-analysis suggested that the rs1800629 polymorphism in TNF-α was a risk factor for asthma." (PMID 24936650, 2014). "Subgroup analyses found that the TNF-α rs1800629 polymorphism was significantly associated with asthma risk in West Asians and South Asians (OR = 2.47, 95% CI = 1.48–4.12, P = 0.0005; OR = 1.83, 95% CI = 1.42–2.36, P<0.00001), but not East Asians and Caucasians." (PMID 24936650, 2014). "These accumulated data support the idea that TNF-α plays an important role in the pathogenesis of asthma and the TNF-α gene may be a susceptibility gene of asthma." (PMID 24936650, 2014). "Several studies have shown that high serum TNF-α level is linked to hyperresponsiveness in asthma." (PMID 24936650, 2014). "Haplotype analysis also revealed two haplotypes (ATA haplotype of IL-4Rα A1199>C, IL-4Rα T1570>C and IL-4Rα A1727>G and CA haplotype of TNFα C-863>A and TNFα G-308>A polymorphisms) which were significantly associated with difficult asthma in children (p = 0.04 and p = 0.018, respectively)." (PMID 23573270, 2013). "Furthermore, the G-308>A polymorphism was in strong linkage disequilibrium with C-863>A and carriage of the CA haplotype (TNFα -863C and -308A) has been significantly associated with difficult asthma, even after correction for multiple testing." (PMID 23573270, 2013).
asthma (continued). "Thus, the carriers of genotypes, which are associated with higher TNF production, demonstrated more frequency of asthma, higher levels of neutrophil elastase, and decrease of bone density." (PMID 23343370, 2013). "The suppression of all the symptoms of asthma in the present study was associated with reduced levels of various Th1 cytokines (TNF-α, IL-6, and IL-1β), with reduced levels of various Th2 cytokines (IL-4, IL-5 and IL13) and with reduced levels of a Th17 cytokines (IL-17F) in splenocytes." (PMID 23346203, 2012). "In addition, the ACE D/I, FcεRIβ -6843G/A, TNF-α -308G/A, IL-13 -1923C/T and IL-13 -2044A/G polymorphisms were associated with asthma risk in Chinese adults." (PMID 20868478, 2010). "Interestingly, in rat asthma model, IκB kinase-2 inhibitor cause significant dose-related and time-dependent inhibition of TNF-α." (PMID 19706153, 2009). "CD38 has a role in airway hyperresponsiveness, a hallmark of asthma, since deficient mice develop attenuated airway hyperresponsiveness compared to wild-type mice following intranasal challenges with cytokines such as IL-13 and TNF-α." (PMID 18341691, 2008). "Furthermore, in refractory asthma, treatment with etanercept, an anti-TNFα measure, is associated with improvement in asthma symptoms, lung function, and airway hyperresponsiveness." (PMID 18234086, 2008). "Among cases with non-smoking parents, carrying one copy of the ht6 (CACCGA) haplotype containing the TNF-238A allele or one copy of the ht5 haplotype exhibited an increased risk of asthma (RR = 2.15; 95% CI, 1.21–3.82; p = 0.0082 for ht5; RR = 2.40; 95% CI, 1.18–4.81; p = 0.014 for ht6)." (PMID 17450233, 2007). "Our results suggest that genetic variation in TNF may contribute to childhood asthma and that associations may be modified by parental smoking." (PMID 17450233, 2007). "Among cases without smoking parents in the home, the TNF-308A allele and TNF-238A alleles showed increased risk of asthma (RR = 2.06; 95% CI, 1.19–3.55; p = 0.0097; false discovery rate = 0.04 for TNF-308A; RR = 2.21; 95% CI, 1.14–4.30; p = 0.019; false discovery rate = 0.04 for TNF-238A)." (PMID 17450233, 2007). "Inflammatory diseases such as TNF-α-associated asthma may be treatable by GAC1 as a novel therapy." (PMID 39263346, 2024). "Additionally, changes in the inflammatory cytokines from fat, such as tumor necrosis factor-alpha, leptin, and adiponectin, could increase airway sensitivity and elevate the risk of lung conditions such as asthma." (PMID 39441792, 2024). "Likewise, stamen extract of Mesua ferrea L. (Calophyllaceae) from the Calophyllaceae family and root extract of Clerodendrum serratum of the genus Clerodendrum is reported to ameliorate allergic asthma through the modulation of few asthma-associated cytokines like TNF-α, IL-5, and IL-4." (PMID 37251328, 2023). "A systematic review concluded that TNF-α and IL-6 may influence the risk of asthma." (PMID 37020645, 2023). "Inflammatory cytokines could promote asthma airway inflammatory cells infiltration, and Th1 inflammatory cytokines (IFN-γ, TNF-α) or Th17 inflammatory cytokines (IL-17A) are more likely to be associated with steroid-resistant asthma (Hansbro, Kaiko & Foster, 2011)." (PMID 35602900, 2022). "Moreover, a high level of cytokines other than TNF-α may support the systemic inflammation that occurs in COPD with asthma cohort, which is associated with chronic airway damage in the disease." (PMID 32092112, 2020). "This asthma-associated composition furthermore correlated with lower levels of topical pro-inflammatory airway immune mediators (IL-1β and TNF-α), which may characterize an inefficient anti-bacterial response, and higher levels of monocyte and T-cell recruiting chemoattractants (CCL2 and CCL17)." (PMID 31676759, 2019).
asthma (continued). "Also for this cytokine, human association studies have demonstrated a correlation between asthma and certain genetic polymorphisms, and high TNF-α levels in the blood could be related to severe forms of the disease and steroid insensitivity." (PMID 31826038, 2018). "We examined the association between self-reported racial/ethnic discrimination and bronchodilator response (BDR) among African American youth with asthma ages 8 to 21 years (n = 576) and whether this association varies with tumor necrosis factor alpha (TNF-α) level." (PMID 28609485, 2017). "Upregulation of TNF-α production that depletes cellular antioxidants and increases susceptibility of lung tissues to oxygen radicals is associated with various lung diseases, including asthma, chronic bronchitis, COPD, emphysema, pulmonary fibrosis, and acute respiratory distress syndrome (ARDS)." (PMID 28747201, 2017). "IL-6 was associated in the asthma group with age (β = 0.19 [95% CI, 0.11–0.27]) and BMI (β = 0.25 [95% CI, 0.17–0.32]), as well as hsCRP (β = 0.6 [95% CI, 0.54–0.67]), fibrinogen (β = 0.29 [95% CI, 0.22–0.37]), TNFα (β = 0.29 [95% CI, 0.22–0.37]), and ETP (β = 0.35 [95% CI, 0.28–0.42])." (PMID 28429138, 2017). "Thus, the results of meta-analysis carried out to explore the association between the TNFα –308GA polymorphism and asthma development suggested that TNFα –308A allele may be a risk factor in the etiology of the disease." (PMID 23343370, 2013). "Reduced vitamin D levels are associated with increased expression of TNF-alpha, suggesting that enhanced expression of this pro-inflammatory cytokine is a potential pathway by which reduced vitamin D levels could exert pro-inflammatory effects in asthma." (PMID 23432854, 2013). "Therefore, genetic polymorphisms that affect gene expression or TNF activity in the airways might be expected to influence asthma risk." (PMID 17450233, 2007). "Taken together, these findings suggest that TNF-α production is generally elevated during virus-induced asthma exacerbations." (PMID 41576028, 2026). "Significant decreases in TNF-α concentrations were detected in asthma subpopulations, while improvements in small airway function (FEF25-75) were mostly reported in COPD patients." (PMID 41555409, 2026). "Elevated IL-4, IL-9, and TNF-α were observed in non-T2 asthma compared with T2-high asthma, while children exhibited higher levels of IL-2, IL-6, IFN-γ, and IL-17A than adults." (PMID 41601686, 2026). "Mechanistic studies have established that non-T2 asthma involves prominent activation of Th1 and Th17 responses, with key roles for IL-6, IL-17A, and TNF-α in driving neutrophilic inflammation and airway hyperresponsiveness." (PMID 41601686, 2026). "Initial studies with small patient populations showed that anti-TNF treatment improved asthma-related quality of life, airway hyperresponsiveness, lung function, and exacerbation frequency." (PMID 41155381, 2025). "During the acute phase of asthma, the levels of TNF-α induced by inhaling P. fusca and P. ficariae were lower than those in the ovalbumin group." (PMID 40558541, 2025). "Resistin is linked to asthma, COPD, fibrosis, and acute lung injury, while adiponectin suppresses pulmonary inflammation by inhibiting TNF-α, IL-6, and chemokine production." (PMID 40453581, 2025). "In severe asthma, macrophages adopt the M1 phenotype and produce a large amount of pro-inflammatory mediators (including TNF-α, IL-1β, IL-6, NO, etc.)that promote airway mucus secretion, exacerbate lung injury, and accelerate airway remodeling." (PMID 40661956, 2025). "For instance, anti-TNF-α was initially tried in asthma and COPD, but antagonizing TNF-α instead caused the occurrence of anti-TNF-α-related lung diseases, such as interstitial lung diseases." (PMID 39861052, 2025). "Clinical trials have shown that neutrophilic-targeted biologic agents for severe asthma, such as anti-IL-17 and anti-TNF-α antagonists, are ineffective." (PMID 40313547, 2025).
asthma (continued). "Tumor necrosis factor-alpha (TNF-α): It is a cytokine that promotes inflammation and significantly contributes to the pathophysiology of asthma, especially in severe cases and those resistant to corticosteroids." (PMID 40564060, 2025). "This has been linked to increased levels of cytokines, such as IL-18, IL-6, TNF-α, leukotrienes, and chemokines, in patients with asthma." (PMID 40770020, 2025). "This revealed elevated levels of the asthma-promoting cytokine IL-4 and TNFα, with TNFα levels returning to baseline following nociceptor ablation." (PMID 39229121, 2025). "Asthma patients exhibit elevated levels of inflammatory mediators (e.g., interleukins, tumor necrosis factor), which can interfere with calcium metabolism and distribution." (PMID 40469921, 2025). "Emerging evidence suggests shared mechanisms between asthma and fibromyalgia, including neurogenic inflammation mediated by cytokines (e.g. IL-6, TNF-α) and central sensitization." (PMID 41017472, 2025). "Oral administration of L. reuteri ATCC 23272 also resulted in immunoregulatory effects, with elevated IL-10 levels and reduced levels of IL-5, IL-13, MCP-1, and TNF-α in OVA-induced asthma mice." (PMID 39820222, 2025). "The relationship between the A/L ratio and proinflammatory cytokines IL-6, IL-8 and TNFα playing a pathogenetic role both in patients with asthma and in patients with abdominal obesity was also studied." (PMID 40361972, 2025). "Our study revealed an inverse relationship of the A/L ratio with the number of eosinophils in peripheral blood, as well as with proinflammatory cytokines, such as IL-6, IL-8 and TNFα in patients with asthma." (PMID 40361972, 2025). "The targets of the FEO‐03 network, IL13, and functional partners IL13RA1, IL13RA2, IL4R, IL6, and TNF were presented in a red box from the asthma diagram of KEGG Pathways." (PMID 40777200, 2025). "In severe asthma, where neutrophils are dominant, T-helper 17 (Th 17) cells secrete IL-17 A, IL-17 F, IL-21, IL-22, and TNF-α which drive inflammation and airway hyperresponsiveness." (PMID 40605076, 2025). "The direct effect of asthma leading to osteoporosis is related to disease inflammation (e.g., neutrophil-mediated inflammation, TNF-α and IL-6)." (PMID 39857779, 2025). "The asthma group had elevated IgE levels, and inflammation, as expressed by cytokines (TNF-α, IL-6, IL-8, IL-4, IL-17A, and IL-13), was highest in the NOS group." (PMID 40997602, 2025). "Pro-inflammatory cytokines such as IL-6 and TNF-α, which are elevated in asthma, can stimulate bone resorption, reducing bone mineral density (BMD)." (PMID 39857779, 2025). "Our study showed that TNF-α was the only cytokine that significantly increased during the high-PM2.5 exposure in comparison with the period of low-PM2.5 exposure in the asthma group." (PMID 40217808, 2025). "Although initial studies of anti-TNF treatments (like infliximab and etanercept) indicated some benefits for certain patients with severe asthma, worries about side effects and infection risks have restricted their use in clinical settings." (PMID 40564060, 2025). "TNF-α levels are increased in both adult and pediatric asthma patients, particularly those with corticosteroid-resistant asthma." (PMID 40573126, 2025). "We examined the correlations of serum IL-36 levels with serum IL-6, IL-8, IL-10, IL-13, IL-17, IFN-γ, and TNF levels, except for IL-4 and IL-5 levels, which were only rarely observed in our asthma patients." (PMID 40115968, 2025). "These biologics, acting as anti-TNF-α, offer a reduction in systemic inflammatory load and improvement in asthma outcomes." (PMID 40337626, 2025). "TNF-α, a prototypical member of the TNF protein superfamily, plays a critical role in various pathological conditions, including inflammation, infection, and asthma, with markedly elevated TNF-α levels observed in affected tissues." (PMID 41181101, 2025).
asthma (continued). "Anti-TNF-α treatments have been shown to improve lung function, reduce airway hyperreactivity, and enhance the quality of life in asthma patients, while also decreasing the frequency of acute exacerbations." (PMID 40165005, 2025). "Serving as a foundational element in asthma therapy, TNF can interact with TNF-like ligands and IL33 to trigger allergic airway inflammation, which has also been regarded as a marker for allergic pulmonary disorders." (PMID 40420184, 2025). "Studies have shown that TNF-α, which is found in higher levels in severe asthma cases, contributes to the disruption of barrier function and the activation of cells within bronchial epithelial tissue." (PMID 40558541, 2025). "The potential of farnesol in asthma treatment is further supported by its ability to modulate inflammatory mediators such as COX2 and TNFα, which are crucial in asthma pathophysiology." (PMID 40598285, 2025). "In patients with severe asthma, pro-inflammatory cytokines in the airway lumen and bronchial mucosa, including TNF-α, IL-1β, IL-6, and IL-8, are mainly produced by macrophages, while LPS can stimulate THP-1 cells to secrete pro-inflammatory cytokines." (PMID 40661956, 2025). "LIGHT is a member of the tumor necrosis factor (TNF) superfamily, a type II transmembrane glycoprotein that plays an important role in inflammatory diseases such as autoimmune hepatitis, urticaria, asthma, and nonalcoholic fatty liver." (PMID 40356928, 2025). "When analyzing cytokine distribution according to asthma severity, we found higher median concentrations of TNF‐α in the severe‐asthma group compared with the non‐severe group (2.8 vs. 1.9 pg/mL; p = 0.043)." (PMID 41159221, 2025). "A study assessing the role of the tumor necrosis factor-alpha (TNF-alpha) antagonist etanercept in refractory severe asthma monitored sputum IL-8 levels during treatment." (PMID 40863432, 2025). "As a central mediator of airway inflammation in asthma, TNF-α levels have also been shown to be significantly increased in the BALF of OVA-induced mice, as demonstrated in this study." (PMID 41181101, 2025). "TNF-α dysregulation is connected to inflammatory conditions such asthma, rheumatoid arthritis, and inflammatory bowel diseases." (PMID 41155381, 2025). "After mast cell and/or basophil meets an allergen, leukotriene D4 and PGE2 are produced within 30 min, and within several hours, TNF-α and IL-4 are released in various situations such as asthma, allergic rhinitis, and atopic dermatitis." (PMID 40323927, 2025). "TNF-α acts as a proinflammatory agent and exacerbates airway hyperresponsiveness in asthma, while IL-6 plays a role in both inflammation and Th2 cell differentiation." (PMID 39421735, 2024). "TNF sputum marker activity correlates with asthma severity and decreases after azithromycin treatment." (PMID 38339210, 2024). "TNF-α promotes the recruitment of innate immune cells, including eosinophils and neutrophils, to the airway during asthma exacerbation." (PMID 39902293, 2024). "IL-17 and TNF-α cytokines are essential in neutrophil infiltration within the lungs of asthma patients, and their decline indicates an attenuating of neutrophilic inflammation." (PMID 39770422, 2024). "Particularly, COS (<1 kDa) showed a protective effect of OVA-induced lung inflammation in mice with asthma by reducing inflammatory parameters in the lung tissue, such as IL-4, IL-5, IL-13, and TNF-α." (PMID 39203729, 2024). "It is increased in the airways of severe asthma patients, and murine studies have confirmed the function of TNF in promoting bronchoconstriction and airway hyperresponsiveness (AHR)." (PMID 38540714, 2024). "Chronic airway inflammation in asthma, characterized by elevated cytokine levels such as IL-4, IL-5, IL-13, and TNF-α, can contribute to systemic effects that, in turn, influence the CNS." (PMID 40474934, 2024).